ENSG00000281863
Synonyms: LOC124900561
Gene: Small nucleolar RNA gene on chromosome 3 (8,931,495 to 8,931,632, forward strand). Ensembl gene ENSG00000281863.
Gene Ontology:
Biological process: RNA processing
Cellular component: nucleolus
Homologues: Orthologues: mouse Gm22504 (76% identical), mouse Gm23377 (75% identical), rat LOC120094467 (72% identical), rat LOC120099461 (72% identical). Paralogues in human: SNORA17B (79% identical), SNORA17A (57% identical).